PTCSC2 (papillary thyroid carcinoma susceptibility candidate 2)
Gene: Long non-coding RNA gene on chromosome 9 (97,699,625 to 97,853,116, reverse strand). Ensembl gene ENSG00000236130.
Diseases named in the same sentence as PTCSC2 in open-access papers:
PTCSC2 is named in the same sentence as 15 diseases in open-access papers, as found by Europe PMC text mining. Sharing a sentence is not in itself a finding about the gene and the disease. The quoted sentences say what the papers report.
thyroid cancer (15 papers, 2016 to 2024). "The purpose of this study was to survey the associations of six single nucleotide polymorphisms (SNPs) in the TMOD1 and PTCSC2 genes with thyroid carcinoma (TC)." (PMID 36316666, 2022). "TMOD1 polymorphism was detected to be markedly decreased, and PTCSC2 was detected to be markedly increased in thyroid carcinoma risk based on our analysis." (PMID 36316666, 2022). "Studies of the mechanism between TMOD1 and PTCSC2 polymorphisms and thyroid carcinoma should be conducted to explore the effect." (PMID 36316666, 2022). "In our results, we found that the association between the polymorphism of TMOD1 and PTCSC2 polymorphisms and thyroid carcinoma risk was affected by age and sex." (PMID 36316666, 2022). "In this study, we assessed the association of the TMOD1 (rs1052270, rs10982622, and rs1475545) and PTCSC2 (rs16924016, rs925489, and rs965513) gene polymorphisms with susceptibility to thyroid carcinoma." (PMID 36316666, 2022). "In conclusion, we found that TMOD1 and PTCSC2 were correlated with thyroid carcinoma risk in the Chinese Han population." (PMID 36316666, 2022). "Papillary thyroid carcinoma susceptibility candidate 2 (PTCSC2), as a thyroid tissue-specific long intergenic noncoding gene, includes unsliced and spliced isoforms demonstrating thyroid-specific expression." (PMID 36316666, 2022). "In thyroid carcinoma, several papillary thyroid carcinoma susceptibility candidates, such as PTCSC2, contain a risk-variant rs965513, and PTCSC3 encompasses rs944289; two lincRNA expression levels are strongly down-regulated in thyroid carcinoma tissues." (PMID 32523949, 2020). "Therefore, we wanted to investigate the association of rs16924016, rs925489, and rs965513 on PTCSC2 with thyroid cancer and their interaction." (PMID 36316666, 2022). "Due to ethnic and population differences, this study investigated whether six polymorphic loci of TMOD1 and PTCSC2 were related to the susceptibility of thyroid carcinoma to further reveal the genetic pathogenesis of thyroid diseases in the Chinese population." (PMID 36316666, 2022). "In addition, our study is the first to report the association between PTCSC2 rs925489 and thyroid carcinoma risk." (PMID 36316666, 2022). "PTCSC2 may work synergistically with rs965513 to cause thyroid cancer." (PMID 32596158, 2020). "Another such example is lncRNA PTCSC2 which interacts with MYH9 and, thus, reverses MYH9-mediaed inhibition of activities of a bidirectional promoter shared by FOXE1 and PTCSC2 in thyroid cancer." (PMID 37072811, 2023). "MYH9 binds to lncRNA gene PTCSC2 (Papillary Thyroid Carcinoma Susceptibility Candidate 2) and regulates FOXE1 (Forkhead box protein E1) in the 9q22 thyroid cancer risk locus." (PMID 37175943, 2023). "MYH9 acted as a suppressor gene in thyroid cancer by binding to the promoter region of lncRNA PTCSC2 and promoting forehead box E1 activation." (PMID 35318312, 2022). "In thyroid cancer, lncRNA PTCSC2 has been confirmed to interact with MYH9 to regulate FOXE1 expression." (PMID 35541917, 2022). "At present, there have been few studies on the role of PTCSC2 in thyroid cancer, and more research is needed to determine their relationship." (PMID 32596158, 2020). "A study involving 65 thyroid cancer tissues found that both folded and unfolded PTCSC2 were expressed at lower levels than in normal thyroid tissues." (PMID 32596158, 2020). "In PTC, MYH9 binds the lncRNA gene, PTCSC2, to modulate FOXE1 in the 9q22 thyroid cancer risk locus." (PMID 32982961, 2020). "Rs16924016 is an intron variant located in PTCSC2 and has not reported to be associated with thyroid cancer." (PMID 36316666, 2022). "Although MYH9 binds to lncRNA gene PTCSC2 and regulates FOXE1 in the 9q22 thyroid cancer risk locus, mechanistically, the detailed role of MYH9 in PTC is still unknown." (PMID 32982961, 2020). "Generally, the risk allele may involve in the reduction of PTCSC2 and PTCSC3 expression and the increased risk of thyroid cancer." (PMID 29416703, 2018).
thyroid cancer (continued). "Recently, a class of long intergenic noncoding RNAs named papillary thyroid cancer susceptibility candidate (PTCSC), such as PTCSC1 (located in 8q24), PTCSC2 (located in 9q22) and PTCSC3 (located in 14q13), might predispose infected persons to thyroid cancer." (PMID 29416703, 2018). "Sedaghati summarized the dysregulated and functional LncRNAs in thyroid cancer, including 28 upregulated LncRNAs, such as ANRIL, BANCR, H19, HOTAIR, MALAT1, and NEAT1, and 22 downregulated LncRNAs, including GAS5, NAMA, PTCSC2, and PTCSC3." (PMID 37874339, 2024). "Both PTCSC2 and PTCSC3 can play an important anti-tumor role by affecting the expression levels of other genes in thyroid cancer, but the specific mechanisms require further investigation." (PMID 29416703, 2018). "For instance, PCAT1, PVT1, and PCAT19 in prostate cancer, CUPID1 and CUPID2 in breast cancer, PTCSC2 and PTCSC3 in thyroid cancer, LINC00673 in pancreatic cancer, lncPSCA in gastric cancer, as well as LCETRL3 and LCETRL4 in non-small cell lung cancer, are implicated in malignant development." (PMID 37072811, 2023). "Meanwhile, PTCSC2, LINC02178, SRP14-AS1, and MIR22HG have been mainly reported in other cancer types, such as head and neck squamous cell carcinoma, oral and oropharyngeal squamous cell carcinoma, and thyroid cancer.TMEM99 has not been reported previously." (PMID 36333719, 2022).
papillary thyroid cancer (7 papers, 2016 to 2023). "Specifically, rs4297160 is located within the lincRNA gene PTCSC2, which has been linked to a predisposition for papillary thyroid cancer." (PMID 35977827, 2022).
hypothyroidism (2 papers, 2022 to 2023). Abnormally low levels of thyroid hormone. "In European populations, the rs965513 in PTCSC2 was strongly related to PTC for hypothyroidism, thyroid hormone levels, and other thyroid diseases." (PMID 36316666, 2022). "Rs925489 on PTCSC2 was correlated with low TSH levels and hypothyroidism." (PMID 36316666, 2022).
tumor (4 papers, 2017 to 2022). "Papillary thyroid cancer susceptibility candidate 2 (PTCSC2) and 3 (PTCSC3) are two novel thyroid-specific lncRNAs that may serve as tumor suppressors." (PMID 27802187, 2017). "Significant correlation was observed between the risk allele [A] of single nucleotide polymorphism (SNP) rs965513 and the low expression levels of PTCSC2, FOXE1, and TSHR in non-tumor thyroid tissues along with high PTC risk, suggesting that there might exist a multilayer regulatory network." (PMID 29416703, 2018). "The expression levels of PTCSC2 and PTCSC3 are strongly down-regulated in PTC tumor tissues and in TC tissues, respectively, compared with neighboring normal tissues." (PMID 27802187, 2017). "The expression levels of PTCSC2 and PTCSC3 are strictly thyroid-specific, and they may serve as promising tumor suppressors." (PMID 29416703, 2018).
PTCSC2 also shares sentences with these, for which no sentence is quoted: breast carcinoma (1 paper); cancer (1); gastric cancer (1); head and neck squamous cell carcinoma (1); lymph node metastasis (1); non-small cell lung carcinoma (1); oropharyngeal squamous cell carcinoma (1); pancreatic cancer (1); prostate carcinoma (1); thyroid (1); thyroid tumor (1).